CD47 (CD47 molecule)
Diseases named in the same sentence as CD47 in open-access papers (continued):
Sharing a sentence is not in itself a finding about the gene and the disease.
cancer (continued). "We next investigated the therapeutic impact of mAbs blocking CD47 and/or SIRPα on gastroenterological tumors in immunocompetent mouse models equipped with syngeneic immune responses between cancer and immune cells." (PMID 30460349, 2018). "Intriguingly, researchers found that CD47 was expressed on all cancer cells from patients, pointing out that it is necessary to investigate the expression of CD47 in EC." (PMID 30525058, 2018). "As the characteristics of the cancer cell membrane depend on its membrane proteins, we identified five major proteins associated with cell invasion and metastasis (CD44, CD47, E-cadherin, EpCAM, and Tissue factor) using western blot." (PMID 30487569, 2018). "Cancer cells regulate the expression levels of immune checkpoints and inhibit killing effects of host immune systems, so genes regarding the immune checkpoints, including PD-L1 and CD47 have become potential targets for cancer immunotherapies." (PMID 29416769, 2018). "CD47, being ubiquitously expressed on normal cells and upregulated on many cancer cells, has been extensively studied in the context of “don’t-eat-me”." (PMID 30400822, 2018). "Caspase-independent cell death has been observed in a variety of cancer treatments, such as ionizing radiation, CD47 agonist peptides, berberine, differentiation inducing factor 3, geranylated 4-phenylcoumarins, among others." (PMID 29298674, 2018). "CD47 is over expressed on many different human cancers and it is also known as a “don’t eat me” signal." (PMID 30400822, 2018). "Successful cancer clones possess mechanisms to modify these signals or to express CD47 to evade PrCR." (PMID 30097573, 2018). "Together, targeting innate immune checkpoint CD47 is a safe and excellent strategy as a monotherapy or in combination with other anti-cancer therapy." (PMID 30062558, 2018). "Many studies have demonstrated that there is great potential for targeting the CD47-SIRPα pathway as therapy for cancer." (PMID 30400822, 2018). "Surface exposed CD47 is often up-regulated by cancer cells to avoid clearance by phagocytes and to suppress immunogenic cell death (ICD) elicited by anticancer therapies." (PMID 29707136, 2018). "CD47-targeted therapeutics have been developed to overcome this immune checkpoint for cancer treatment." (PMID 30643501, 2018). "To answer the first question, we performed a genomic regulatory analysis to locate the CD47 cis-regulatory regions or enhancers active in cancer cells." (PMID 28378740, 2017). "Since that publication there have been additional studies examining the safety and efficacy of targeting CD47 as an anti-cancer therapeutic." (PMID 28100392, 2017). "Of particular relevance to transmissible cancers, which are both allografts and cancer, CD47 appears to play a crucial role in transplant tolerance." (PMID 28515726, 2017). "Humanized anti-CD47 Abs have entered early clinical trials in the treatment of various types of cancers (clinicaltrials.gov)." (PMID 29050218, 2017). "Differential expression of CD47 between cancer and the normal urothelium in the bladder makes it a good cancer imaging target." (PMID 28839158, 2017). "Since stimulating MCF7 cells with TNF-α increases CD47 expression, we then blocked the TNF pathway as a possible translational approach to reduce CD47 expression and aid phagocytosis of the cancer cells." (PMID 28378740, 2017). "We used ScFv (single chain variable fragment) from mouse CD47 antibody to generate CD47-CAR-T cells for targeting different cancer cell lines." (PMID 29065481, 2017). "The present report demonstrates a high activity of CD47-CAR-T cells against cancer cell lines with a high expression of CD47." (PMID 29065481, 2017). "CD47-CAR-T cells effectively killed ovarian, pancreatic and other cancer cells and produced high level of cytokines that correlated with expression of CD47 antigen." (PMID 29065481, 2017).
cancer (continued). "Flow-cytometry showed that 46% of the macrophages engulfed cancer cells after the CD47 signal was blocked, which was much higher than that of the anti-HLA antibody group or the IgG1 isotype group." (PMID 28380460, 2017). "We show that a set of active constituent enhancers, located within the two CD47 SEs, regulate CD47 expression in different cancer cell types and that disruption of CD47 SEs reduces CD47 gene expression." (PMID 28378740, 2017). "Despite all this information, the mechanisms and upstream regulators responsible for increasing CD47 expression in cancer cells are still poorly understood." (PMID 28378740, 2017). "Since inhibitory antibody administration is more clinically applicable, we further blocked the CD47 pathway in both SK-OV-3 cells and primary patient cancer cells using the anti-CD47 mAb, BRIC126." (PMID 28380460, 2017). "As of November 13, 2016, there are eight phase I clinical trials that are investigating the effect of blocking CD47-SIRPα signaling axis in various cancer patients." (PMID 28077173, 2017). "An example of using this strategy is the over expression of CD47 on the cancer cell surface, which labels the cells with the “self” marker and correlates with poor clinical prognosis." (PMID 28220118, 2017). "Remarkably, if CD47 is blocked by an anti-CD47 antibody then a variety of cancers can be cleared from mice." (PMID 28977832, 2017). "We used mouse monoclonal B6H12 CD47 antibody to detect CD47 in different cancer cells line by FASC staining." (PMID 29065481, 2017). "Our data highlight a potentially overlooked effect of cancer immunotherapy using anti-CD47 antibodies." (PMID 27283989, 2017). "CD47 has been reported to be overexpressed on a variety of cancer cell types in order to suppress phagocytosis of these cells." (PMID 28977832, 2017). "Using an anti-CD47 mAb, we found that CD47 inhibition in both SK-OV-3 cells and primary cancer cells was able to recapitulate our knockdown results and led to an increase in the number of infiltrating macrophages." (PMID 28380460, 2017). "Recently it has become clear that most human cancer cells overexpress CD47 on their surface apparently to prevent themselves being phagocytosed; their phagocytosis being promoted by the presence of calreticulin on the surface of the cancer cells." (PMID 28977832, 2017). "Most human cancers overexpress CD47, and antibodies to CD47 have shown a remarkable ability to clear a range of cancers in animal models." (PMID 28977832, 2017). "Despite these findings, CD47 remains an intriguing therapeutic target and warrants further exploration of alternative approaches to use CD47 blockade to overcome immune evasion mechanisms established by cancer cells." (PMID 28234345, 2017). "To better understand the regulatory genomic landscape of CD47, we analysed publicly available H3K27ac ChIP-Seq data for different cancer cell lines." (PMID 28378740, 2017). "Given its essential role as a negative checkpoint for innate immunity and subsequent adaptive immunity, CD47-SIRPα axis has been explored as a new target for cancer immunotherapy and its disruption has demonstrated great therapeutic promise." (PMID 28077173, 2017). "CD47 expression is elevated in varying cancer cells, and injection of blocking antibodies against CD47 to block CD47-SIRPα signaling has been shown to induce antitumor immune responses." (PMID 27283989, 2017). "Under pathological conditions, CD47 expression on the cancer cell membrane suppresses the phagocytic activity of immune cells and is associated with poor prognosis of bladder cancer, leukemia, non-Hodgkin's lymphoma, and breast cancer." (PMID 28380460, 2017). "Although this is directly related to phagocytosis of cancer cells by macrophages, CD47 blockade also triggers anti-cancer T cell responses through macrophages as well as dendritic cells (DCs)." (PMID 29050218, 2017).
cancer (continued). "The average expression of CD47 in all tested cancer cells lines was significantly higher than in normal cell lines." (PMID 29065481, 2017). "Our data are consistent with the anti-CD47 antibody killing cancer cells by antibody-dependent cellular phagocytosis (ADCP)." (PMID 28977832, 2017). "It has been reported that increased expression of CD47 enables cancer cells to evade phagocytosis by macrophages and promotes the CSC phenotype." (PMID 29187162, 2017). "Another anti-cancer therapeutic approach to block CD47 was demonstrated with the use of CD47 siRNA or CD47 shRNA." (PMID 29065481, 2017). "The CD47-CAR-T cells demonstrated cytotoxic activity against cancer cell lines and produced cytokines that correlated with the level of CD47 expression." (PMID 29065481, 2017). "Our in silico analyses suggest that cancer types characterized by the presence of CD47 SEs have high levels of CD47 transcript." (PMID 28378740, 2017). "This suggests that rather than needing to target a specific pathway, such as the CD47-SIRPα pathway, phagocytosis of cancer cells can be increased simply by targeting cell surface markers that are highly expressed." (PMID 28977832, 2017). "This is the first report that demonstrates the efficacy of CD47-CAR-T cells against different cancer cells in vitro and in vivo in a pancreatic BcPC3 xenograft model." (PMID 29065481, 2017). "CD47 antibody detected a higher level of CD47 expression in cancer cell lines versus normal keratinocytes and 293 cells." (PMID 29065481, 2017). "Other PIQ analysis predicts the location of binding motifs for NFKB family members within the functional CD47 E7, which is active in other cancer cell lines besides MCF7." (PMID 28378740, 2017). "Expression of CD47 and its interaction with SIRPa leads to the inhibition of macrophage activation and protects cancer cells from phagocytosis, resulting in cancer cell proliferation." (PMID 29312320, 2017). "CD47 transcripts were also more rapidly upregulated in MCF7 than in the low-CD47-expressing, HepG2 cancer line." (PMID 28378740, 2017). "Taken together, our findings suggest that targeting CD47 is an attractive therapeutic anti-cancer approach." (PMID 28234345, 2017). "A number of mechanisms are emerging to be involved in upregulation of CD47 expression in cancer cells." (PMID 29050218, 2017). "We also found that a third functional enhancer, E7, located within the upstream CD47 SE, drove reporter expression in all of the cancer cell lines tested." (PMID 28378740, 2017). "In vitro phagocytosis assays demonstrated that blocking the TNF pathway with infliximab increases phagocytosis of the cancer cells, and the effect is greater if infliximab is combined with an anti-CD47 blocking antibody (clone Hu5F9-G4)." (PMID 28378740, 2017). "We have previously found that antibodies that block the interaction of CD47 with macrophage surface SIRPα release the macrophage to phagocytose and destroy the cancer cells." (PMID 28378740, 2017). "Here the authors identify two SE regions regulating the expression of CD47, a protein expressed by cancer cells to avoid phagocytosis by macrophages, thus suggesting a potential mechanism of immune surveillance escape." (PMID 28378740, 2017). "CD47 enabled the cancer cell to evade immune-surveillance and attack by sending “don't eat me” signal to phagocytic cells, such as macrophages and dendritic cells (DCs), via binding SIRPα, which prevents phagocytosis and T cell activation." (PMID 27863402, 2016). "By inducing inhibitory SIRPα signaling, elevated CD47 expression by some cancers prevents macrophage phagocytosis." (PMID 26840086, 2016). "The functional importance of differential CD47 expression detected in circulating exosomes from healthy versus cancer populations needs further study." (PMID 27819324, 2016). "CD47 overexpression is used by cancer cells to escape from the macrophages-mediated “don’t eat me” signal allowing tumor to progress." (PMID 27839516, 2016).
cancer (continued). "Anti-CD47 antibodies have shown the preclinical activity in different cancers both in vitro and in animal models." (PMID 27671753, 2016). "Studies have demonstrated that macrophage phagocytosis is the major mechanism when treating cancer using antibody therapies aimed to abolish the interaction between CD47/SIRPα." (PMID 27671753, 2016). "Exploiting anti-CD47 antibody-mediated phagocytosis of cancer cells by macrophages, the authors showed increased priming of CD8+ cells but decreased priming of CD4+ cells." (PMID 27212807, 2016). "A significant difference of CD47 expression was observed between exosomes from cancer patients (n = 60) versus exosomes from healthy control (n = 60, p = 0.037)." (PMID 27819324, 2016). "One of the most promising antibody-mediated therapeutic strategies to date is based on inhibiting the interaction between SIRPα and CD47, a transmembrane protein expressed on many cancer cells and CSCs, to allow for increased phagocytosis of cancer cells." (PMID 26980947, 2016). "In line with this, co-regulated BNIP3/CD47 mRNA expression is correlated to cancer progression and poor prognosis." (PMID 27896217, 2016). "CD47 expression is enhanced in mammosphere cultures whereas inhibiting CD47 leads to cancer stem cell depletion in mammospheres." (PMID 27706047, 2016). "Blocking the CD47/SIRPα axe-mediated “don’t eat me” signal allow macrophages to recognize CD47-positive cancer cells with subsequently destroy and elimination through a phagocytosis process." (PMID 27839516, 2016). "The immunofluorescence analysis also indicated that CD47 was over expressed in both cancer cells and inflammatory cells." (PMID 26573233, 2015). "Higher expression of CD47 was also found in various malignancies, which was considered as a mechanism by which cancer cells increase their “selfness”, thus evading macrophage tumoral activity." (PMID 26093091, 2015). "CD47 blockade on cancer cells not only induced macrophage phagocytosis, but also activated antitumor CD8+ cytotoxic T cell response." (PMID 26554307, 2015). "Collectively, CD47 provides a promising target for cancer therapies and have attracted wide interests." (PMID 26554307, 2015). "Of note, the balance between pro-phagocytic calreticulin and anti-phagocytic CD47 has also been described in multiple human cancer cells, with cancer cells often being characterized by CD47 overexpression to elude phagocytic removal." (PMID 25750898, 2015). "In cancer, CD47 blockade was shown to enhance antitumor immunity by stimulating CD8+ cytotoxic T cells." (PMID 26578962, 2015). "Blockade of CD47 by neutralizing antibodies reduces migration and chemotaxis in response to some cancer-derived cells." (PMID 26506238, 2015). "Increased CD47 expression on human AML cells promotes their survival through evasion of phagocytosis, and blocking CD47 on human cancer cells in xenotransplantation models promotes their phagocytosis and elimination by innate immune cells." (PMID 25914882, 2015). "We generated a novel mouse antibody, 5F9, that specifically binds human CD47 and enables phagocytosis of human cancer cells." (PMID 26390038, 2015). "Increased expression of CD47 is proposed to be a mechanism through which cancer cellsevade immune detection and phagocytosis." (PMID 25621565, 2015). "For example, macrophage-mediated cancer cell phagocytosis, resulting in tumor shrinkage, can be restored upon blockade of CD47, a “don’t eat me” signal overexpressed by most cancer cells." (PMID 24723924, 2014). "HEK293 cells were used as opposed to cancer cells in-order to determine the exclusive contribution of the contact- (and hence CD47-) depended effect and to avoid the additional effect of soluble factor secreted by cancer cells over the 72 h period." (PMID 24073274, 2013).
cancer (continued). "This variability may be due to differences in the abundance and types of αv‐family integrins expressed on the membranes of different cancer cells, as well as their likelihood of coexisting with CD47 and the strength of their binding interactions." (PMID 41168993, 2026). "Notably, antibodies like 23C6, potentially targeting the αvβ3 activation state, and αvβ3 inhibitors such as peptides cyclo(─RGDfK) and cilengitide, significantly interfere with the mutually stable coexistence of αvβ3 and CD47 on cancer cell surfaces." (PMID 41168993, 2026). "Thus, β3 and β6 interact with αv, forming dimers on the cancer cell membrane, thereby impacting CD47 expression." (PMID 41168993, 2026). "These may collectively determine the overall necroptotic effects of scaffolded CD47 antibodies on the cancer cells." (PMID 41484790, 2026). "Here, we demonstrated that SIRPA-knockout (KO) iPSC-derived macrophages (iMacs) exhibit superior antitumor activity against various CD47-expressing tumors in vitro when combined with cancer-targeted monoclonal antibodies (mAbs) or chimeric antigen receptors (CARs)." (PMID 42291136, 2026). "Additionally, although disrupting αvβ3/CD47 interactions on the membranes of different cancer cells can enhance macrophage phagocytosis of tumors, but the effectiveness varies." (PMID 41168993, 2026). "Thus, a stable interaction is identified between integrin αvβ3 and CD47 on the cancer cell membrane that facilitates immune evasion and demonstrates that targeting this interaction offers a safer therapeutic strategy for various tumors." (PMID 41168993, 2026). "To rigorously evaluate the hypothesized coexpression of integrin αvβ3 and CD47 on the surface of cancer cells, we conducted an extensive flow cytometric analysis spanning a diverse array of human cell lines." (PMID 41168993, 2026). "Nonetheless, our overall data and message still point to the fact that CD47 blockade could consistently induce MLKL-dependent necroptotic-cell death across a broad array of cancer cell lines and xenograft models." (PMID 41484790, 2026). "Fourth, both activating and inactivating antibodies to αvβ3 could affect the coexistence state of αvβ3 and CD47 on cancer cell membranes." (PMID 41168993, 2026). "Notably, CD47 demonstrated consistently high expression across all four cancer types, whereas forkhead box O1 (FOXO1) exhibited significantly reduced expression in these cancers." (PMID 40396172, 2025). "Additionally, the DSPE-PEG2000-Mal-RS17 peptide (RS17 peptide), a peptide with antitumor properties, targets CD47 in cancer cells, inhibits the CD47–signal regulatory protein alpha (SIRPα) signaling pathway, and increases macrophage engulfment." (PMID 40051791, 2025). "As a transmembrane protein, CD47 interacts with signal regulatory protein alpha (SIRPα) on macrophages, thereby inhibiting phagocytosis and contributing to immune evasion—a mechanism that has garnered increasing interest in cancer research." (PMID 41163221, 2025). "It has been shown that Prr13 upregulation in certain cancer cells leads to a significant downregulation of TSP-1, a protein known for its anti-angiogenic and pro-apoptotic properties, which binds to cell surface receptor CD47 and triggering caspase-independent apoptosis of cancer cells." (PMID 40132035, 2025). "Clinical trial results have shown that targeted therapy against CD47 has achieved significant efficacy in various malignant hematological diseases and solid tumors, making CD47 targeting a potential turning point in cancer immunotherapy." (PMID 40129966, 2025). "Moreover, CD47 has been linked to the induction of EMT, a process associated with increased invasiveness and stemness in cancer cells." (PMID 40765033, 2025).